ADSS2 (adenylosuccinate synthase 2)
Description:
Plays an important role in the de novo pathway and in the salvage pathway of purine nucleotide biosynthesis. Catalyzes the first committed step in the biosynthesis of AMP from IMP.
Synonyms: AdSS 2; ADSS; ADEH
Tractability: Small molecule: a structure with a bound ligand is known; it has a high-quality binding pocket. Antibody: the Human Protein Atlas places it where antibodies can reach. PROTAC: ubiquitination databases record sites on it; a small molecule that binds it is known.
Target class: Enzyme; Ligase
Gene: Protein-coding gene on chromosome 1 (244,408,494 to 244,451,909, reverse strand). Ensembl gene ENSG00000035687.
Subcellular location: Cytoplasm; Mitochondrion
Subcellular location (Human Protein Atlas): Cytosol; Plasma membrane
Pathways (Reactome):
Metabolism: Purine ribonucleoside monophosphate biosynthesis
Gene Ontology:
Molecular function: adenylosuccinate synthase activity; protein binding; GTP binding; phosphate ion binding; magnesium ion binding; nucleotide binding
Biological process: 'de novo' AMP biosynthetic process; AMP biosynthetic process; immune system process; IMP metabolic process; cellular response to electrical stimulus; L-aspartate catabolic process; purine nucleotide biosynthetic process; response to ammonium ion; response to purine-containing compound
Cellular component: extracellular exosome; cytoplasm; cytosol; mitochondrion
Genetic constraint (gnomAD): Loss-of-function variants: 17 observed, 39.5 expected, observed/expected ratio (o/e) 0.43, 90% interval 0.29 to 0.65. The upper end of that interval is the gene's LOEUF score, 0.65, which puts it in group 2 of 6, group 1 being the genes least tolerant of losing a copy. Missense variants: 275 observed, 423.89 expected, observed/expected ratio (o/e) 0.65, 90% interval 0.59 to 0.72. Synonymous variants: 145 observed, 147.14 expected, observed/expected ratio (o/e) 0.99, 90% interval 0.86 to 1.13.
Homologues: Orthologues: chimpanzee ADSS2 (99% identical), macaque ADSS2 (99% identical), dog ADSS2 (98% identical), rat Adss2 (97% identical), mouse Adss2 (97% identical), pig ADSS2 (97% identical), guinea pig ADSS2 (95% identical), rabbit ADSS2 (87% identical), zebrafish adss2 (82% identical), tropical clawed frog adss2 (80% identical), Drosophila melanogaster Adss (60% identical), Caenorhabditis elegans adss-1 (52% identical). Paralogues in human: ADSS1 (75% identical).
Diseases named in the same sentence as ADSS2 in open-access papers:
ADSS2 is named in the same sentence as 27 diseases in open-access papers, as found by Europe PMC text mining. Sharing a sentence is not in itself a finding about the gene and the disease. The quoted sentences say what the papers report.
asthma (2 papers, 2019 to 2025). "Our results suggest PoO effects at the ADSS2 gene, particularly the maternally inherited G‐allele at rs3003214, may contribute to the maternal effect in childhood asthma." (PMID 40133993, 2025). "Alleles at two SNPs—rs3003214 and rs3003211—near the adenylosuccinate synthase 2 gene (ADSS2 on chromosome 1q44) showed significant PoO effects in childhood asthma at a false positive rate (FDR) less than or equal to 0.05." (PMID 40133993, 2025).
ADSS2 also shares sentences with these, for which no sentence is quoted: eczema herpeticum (4 papers); atopic dermatitis (3); schizophrenia (3); cancer (2); glioblastoma (2); allergic disease (1); bipolar disorder (1); bladder cancer (1); breast carcinoma (1); childhood asthma (1); colorectal cancer (1); dilated cardiomyopathy (1); Down syndrome (1); frontotemporal dementia (1); glioma (1); Huntington disease (1); lung adenocarcinoma (1); malignant lymphoma (1); metastatic cancer (1); metastatic tumor (1); myopathy (1); neurodegenerative disease (1); Parkinson disease (1); skin infection (1); tumor (1); viral infections (1).